PLG (plasminogen)
Diseases named in the same sentence as PLG in open-access papers (continued):
Sharing a sentence is not in itself a finding about the gene and the disease.
tumor (continued). "Given that our data suggest that plasminogen supports PDAC disease progression through modifying immune cell activities, it is possible that the contribution of plasminogen to tumor progression in NSG mice could be mitigated." (PMID 37971174, 2024). "It is also important to emphasize the relationship between plasminogen activation in tumors and the presence of IgG fragments whose effects on tumor growth have not been studied." (PMID 39001286, 2024). "It is possible that particularly pathogenic PLG missense variants, like those that cause PDI and PDII, will impair tumor progression and will not be selected in the clonal expansion of a tumor." (PMID 38984351, 2024). "By secreting plasminogen activators, astroglia activate plasmin, which cleaves both Fas-ligand to destroy cancer cells and L1 cell adhesion molecule (L1-CAM) to block adhesion of the tumor cells to the vessel walls." (PMID 37749707, 2023). "Many laboratory data and clinical studies have shown that coagulation-related factors, such as tissue factor (TF), thrombin, plasminogen (PLG), FpA, DDs, TAFI, and thrombin–antithrombin complex, are involved in angiogenesis, tumor cell invasion, tumor progression, and metastasis." (PMID 36105100, 2022). "The uPA converts the proenzyme plasminogen in the serine protease plasmin, involved in a number of physiopathological processes requiring basement membrane (BM) and extracellular matrix (ECM) remodeling, including tumor progression and metastatization." (PMID 35409084, 2022). "In this study, administration of TA suppressed plasminogen activation, and plasminogen produced by tumor cells was not activated and accumulated." (PMID 35371322, 2022). "Most notably, a significant proportion of the ENO1 protein redistributes to the surface of cancer cells, wherein it evolves proteolytic functions through activating the uPAR/plasminogen/MMP axis, thereby contributing to tumor progression in particular the process of metastasis." (PMID 34136381, 2021). "TGF-β regulates uPA expression in cancer cells, while uPA, by plasminogen activation, may activate the secreted latent TGF-β, thus, producing a pernicious cycle which contributes to the enhancement of tumor progression." (PMID 23984088, 2013). "uPA is a secreted serine proteinase that converts plasminogen to plasmin, a trypsin-like serine proteinase, which in turn can degrade a wide variety of ECM components and enable the tumour cells to penetrate the basement membrane, by facilitating cell migration and invasiveness." (PMID 23766912, 2013). "At high expression levels, TSP1 activates the plasminogen/plasmin system and therefore promotes cell invasion; however, reduced TSP1 expression levels promote the interaction between cancer cells and matrix necessary for tumor growth." (PMID 22481923, 2012). "It was found that SAA bound to extracellular matrix components with results of subsequent potential modification of cell binding, enhancement of plasminogen activation, stimulation of matrix metalloproteinase (MMP) production, and increase of the invasive potential of tumor cells." (PMID 22917173, 2012). "In the presence of pro-uPA and plasminogen, the recombinant complex (PrAg-U2 + FP59) was demonstrated to be activated selectively on the surface of uPAR-expressing tumor cells from a broad range of human cancers of different origins, and ultimately resulted in specific tumor cell eradication." (PMID 22069564, 2010). "The clinical significance of this EV-mediated delivery of the plasminogen system is underscored by the identification of uPAR+ extracellular vesicles as robust biomarkers for metastatic disease and by the correlation of exosomal PAI-1 levels with tumor progression and immune evasion." (PMID 41463352, 2025).
tumor (continued). "Additionally, genes involved in extracellular matrix remodelling and adhesion, such as PLAUR, PLG and CEACAM4, may enhance tumour invasion by modifying the tumour microenvironment, a process extensively reported in invasive malignancies." (PMID 40830065, 2025). "However, the potential contribution of plasminogen itself to PDAC tumor growth and metastasis has not been defined." (PMID 37971174, 2024). "Current reports have generally shown that primary tumor growth is independent of plasminogen." (PMID 37971174, 2024). "Nonetheless, a study that compared ELISA and IHC techniques to detect the presence of plasminogen system activation components in human tumour tissue concluded that these two techniques do not have a clear correlation, therefore different study results are probable." (PMID 36831176, 2023). "The plasminogen activation system, comprising the urokinase‐type plasminogen activator (uPA), the cellular receptor for uPA (uPAR), and its specific inhibitor plasminogen activator inhibitor‐1 (PAI‐1 or SERPINE1), is recognized to play a vital role in tumor progression and angiogenesis." (PMID 33512745, 2021). "As a co-receptor of tissue plasminogen activator and plasminogen, ANXA2 promotes the formation and activation of plasmin and the downstream matrix metalloproteinases, and promotes extracellular matrix remodeling, angiogenesis, invasion, and metastasis of tumor cells." (PMID 26362938, 2015). "In addition, in prostate cancer cells TGF-β1 stimulates the expression and activity of uPA, PAI-1, and MMP-9, resulting in a net increment of pericellular plasminogen activation, increased activation of MMP-9, and finally increased tumour cell invasion and metastasis." (PMID 23766912, 2013). "The fact that plasminogen activators are indispensable for tube formation of microvascular cells and that they may induce angiogenesis in vitro strongly suggests a role for uPA and PAI-1 in tumour neovascularisation." (PMID 7547226, 1995). "Our experiments with direct brain injections of tumor cells in the plasminogen knockout mice and EACA treated wild type mice showed no reduction of tumor size compared to the tumors in wild type mice." (PMID 16524486, 2006). "If tumour cells produce proteases capable of releasing endostatin from collagen XVIII, or angiostatin from plasminogen but do not produce proteases that are capable of degrading these antiangiogenic factors, then the tumour may be invasive but angiogenesis and metastases will be limited." (PMID 15545970, 2005).
cancer (165 papers, 1985 to 2025). A tumor composed of atypical neoplastic, often pleomorphic cells that invade other tissues. "As a case study, we focused on the interaction between SERPINE1 and PLAU, two genes known to co-regulate the plasminogen activation system and associated with poor prognosis in multiple cancer types." (PMID 41288989, 2025). "TN facilitates the conversion of plasminogen to plasmin, implicating it in extracellular matrix remodeling associated with cancer development and metastasis." (PMID 40801593, 2025). "It is involved in the plasminogen activation proteolytic cascade in hallmarks of cancer, which has been implicated in cancer cell invasion and metastasis." (PMID 39516345, 2024). "PLG encodes plasminogen, pivotal in hemostasis and involved in multiple biological processes during cancer proliferation and dissemination." (PMID 39179711, 2024). "Proteolysis is a fundamental hallmark of cancer as malignant tumors overexpress proteolytic enzymes for invasion, metastasis and angiogenesis including plasminogen activation system (PAS) and the matrix metalloproteinase family (MMPs)." (PMID 37248432, 2023). "The critical role of the PLG/PLA system in cancer biology is supported by in vivo studies utilizing PLG-deficient mice (Plg−/−)." (PMID 25407528, 2014). "One critical pathway frequently implicated in cancer growth, invasion and spread is the plasminogen (Plg) activation cascade." (PMID 15798771, 2005). "Missense variants in PLG may also play an indirect role in cancer by affecting the type of posttranslational modifications that occur." (PMID 38984351, 2024). "PLG passenger somatic missense variants may be involved in the cancer mutational progression landscape and represents a potentially important point to investigate further." (PMID 38984351, 2024). "The activation of plasminogen by AIIt not only activates pro-matrix metalloproteinases (pro-MMPs) but also induces the angiogenesis of cancer stroma via ECM-associated proangiogenic growth factors, which both play an important role in the invasion and metastasis of cancer." (PMID 36612197, 2022). "The cell surface associated AnxA2 heterotetramer, is a receptor for both plasminogen and tissue type plasminogen activator (tPA) and acts as a catalytic center for the activation of plasminogen to plasmin which helps in invasion and metastasis of cancer cells." (PMID 22957061, 2012). "Together, the plasminogen and urokinase plasminogen activator receptors (uPARs) contribute to the activation of plasmin at the cell surface and the concomitant proteolytic destruction of the pericellular extracellular matrix that is the hallmark of many cancers." (PMID 38069440, 2023). "We hypothesized that cleavage of uPAR is an indication of an active plasminogen activation system and that the amounts of the individual cleavage products would consequently be superior to the total uPAR level as diagnostic markers of cancer." (PMID 19672256, 2009). "Over-expression of PLAUR within activation of the plasminogen system, has been correlated with poor survival and prognosis in several cancers, in addition to being predictive of adverse cardiovascular events." (PMID 41270070, 2025). "This fact corroborates studies that report the expression of ENO1 on the cell surface exceptionally in malignant tumors, where it binds to plasminogen to promote ECM degradation and metastasis." (PMID 40005870, 2025). "Recent findings have demonstrated that the plasminogen activation system is a critical regulator in cancer cells’ invasion and metastasis, which are dependent on extracellular matrix degradation during local angiogenesis." (PMID 39382373, 2024). "PLG is a cancer-related gene based on experiments involving insertional mutagenesis in mice, but it is not considered to be a cancer-driver gene." (PMID 38984351, 2024).
cancer (continued). "Although the role of TN is unclear, it was suggested that the TN activity of enhancing plasminogen activation is responsible for cancer development by remodeling cancer tissues." (PMID 38187250, 2024). "ALDH1A3 is an important player in the progression of several other cancers, hence it will be crucial to evaluate if ALDH1A3 regulates the plasminogen activation pathway in these cancers as well." (PMID 37753740, 2024). "ECRG2 protein was demonstrated to inhibit the activity of a serine protease known as urokinase-type plasminogen activator (uPA), an enzyme involved in the conversion of inactive plasminogen into active plasmin, which is important in cancer metastasis." (PMID 38892042, 2024). "A protein interaction analysis on soluble and cell-associated proteins revealed plasminogen as central interactor, where plasminogen itself facilitates cancer cell migration as well as spheroid formation." (PMID 38255998, 2024). "tPA converts the zymogen plasminogen into the active protease plasmin, and inhibiting eHsp90 in this study led to decreased active plasmin levels, which ultimately reduced cancer cell migration." (PMID 39594828, 2024). "It was revealed that TN accumulates in the extracellular matrix (ECM) in cancer tissues and co-localizes with plasminogen in an invasive front." (PMID 38187250, 2024). "This binding of Tetranectin to plasminogen leads to the activation of plasminogen-cascade that triggers the proteolytic processing and degradation of the extracellular matrix and thereby cancer cell migration and invasion." (PMID 37784035, 2023). "PAI-1 can increase metastasis of cancer cells because it is involved in the activation of plasminogen from a zymogen to an active protease, which then contributes to ECM remodeling by activating MMPs." (PMID 37481560, 2023). "Both the phagocytosis of cancer cells by macrophages and cancer cell invasion are known to be regulated by the plasminogen/plasmin protease system." (PMID 37979915, 2023). "On the other hand, PLAUR and MRC2 are involved in the activation of plasminogen and, although the benefit of targeting these proteins in fibrosis remains to be fully demonstrated, encouraging results have been reported for cancer settings." (PMID 36531712, 2022). "PLAUR belongs to the plasminogen activation system and is widely involved in various cancer-specific processes, including inflammation- and immune- and hypoxia-related pathways." (PMID 36035192, 2022). "There is evidence that activation of plasminogen from cancer cells leads to breakdown of cellular components, which in turn leads to invasion of cancer cells into other areas of the body." (PMID 34991439, 2022). "The ability of cancer cells to dissolve the BM and enter the surrounding stroma by expressing proteolytic enzyme activities such as those of the MMPs family and plasminogen activation system (PAS) is one of the key dogmas for their invasion and metastasis." (PMID 36510219, 2022). "Beside the clear role of plasminogen in cancer, it has been found to play a vital role in the cleavage of cysteine-rich protein 61 (Cyr61), which in turn plays a role in augmenting mesenchymal stem cell-mediated neovascularization in ischemic limbs." (PMID 35008762, 2021). "In contrast, uPAR, a main fibrinolytic factor of cancer cells, forms a complex with urokinase-type plasminogen activator (uPA) and converts plasminogen into plasmin." (PMID 33827473, 2021). "Annexin II, which is a receptor for both tPA and plasminogen (recently reviewed in cancer) is highly expressed in exosomes derived from malignant cells, but less expressed in normal and premetastatic breast cancer cells." (PMID 33669052, 2021). "The plasminogen activation (PA) system plays a key role in cancer; it includes the serine-protease urokinase-type plasminogen activator (uPA)." (PMID 33923400, 2021). "Under normal circumstances, activated astrocytes reject extravasated cancer cells by releasing plasminogen activators." (PMID 34504845, 2021).
cancer (continued). "The glycolytic enzyme alpha-enolase (ENO1) present on the surface of malignant tumor cells has been identified as a metastasis-promoting factor through its function of activating plasminogen." (PMID 34136381, 2021). "Increasing evidence has shown that the cellular receptors for plasminogen play a major role in cancer progression." (PMID 32867190, 2020). "This pleiotropic regulatory effect of plasminogen administration in radiation wounds makes plasminogen a potential new drug candidate for the treatment of radiation-induced skin wounds in cancer patients." (PMID 32205839, 2020). "This makes plasminogen an attractive drug candidate for the treatment of radiation wounds in cancer patients." (PMID 32205839, 2020). "In cancers, the uPA system catalyzes plasminogen to plasmin and directly induces the degradation of the ECM components, which leads to the activation of metalloproteinases and the release of latent growth factors (Laufs, Schumacher & Allgayer, 2006)." (PMID 31218131, 2019). "While the protein is elevated internally in several cancers, it is also actively secreted from tumor cells, where it cleaves plasminogen to create angiostatin." (PMID 30679932, 2019). "A potential molecular target for aggressive cancers is the plasminogen activation system (PAS), which plays a key role in tissue degradation during cancer invasion." (PMID 31694242, 2019). "Collectively, these studies strongly indicate that S100A10 is a central player in facilitating uPA‐mediated cleavage of plasminogen in KRAS‐transformed cancer cells." (PMID 30009399, 2018). "PAI‐1 is a protein encoded by the gene SERPINE1 and is the principal component of the plasminogen system, which is upregulated in inflammation and cancer." (PMID 29573228, 2018). "PLAT, Plasminogen Activator Tissue Type, a serine protease, induces the conversion of inert zymogen plasminogen to protease plasmin, which degrades the surrounding matrix, allowing cancer cells to migrate to distant sites." (PMID 30098229, 2018). "Angiostatin is a proteolytic fragment of plasminogen that has been found to inhibit angiogenesis in cancer." (PMID 29325582, 2018). "Our research group has previously demonstrated that S100A10 (p11) is a receptor for the pro‐protease plasminogen and can drive cancer cell invasion by mediating the conversion of plasminogen into the active protease, plasmin." (PMID 30009399, 2018). "More studies are needed to document if GRN A treatment of cancer cells is able to affect the interaction of ENO1 with plasminogen, uPA and uPAR." (PMID 28415822, 2017). "Plasminogen was activated and converted to plasmin by the binding of uPA and uPAR, initiating pericellular proteolysis and cell migration and contributing to cancer metastasis." (PMID 28978008, 2017). "The activation of the plasminogen system in the process of cancer invasion in numerous types of carcinomas makes uPAR a highly relevant target for therapeutic/theranostic purposes." (PMID 28039488, 2017). "Plasminogen activation and subsequent ECM proteolysis, processes linked to cancer progression and invasion, involve binding of uPA to its cell surface receptor uPAR." (PMID 28506312, 2017). "It was demonstrated nearly two decades ago that angiostatin, a cancer-mediated proteolytic fragment of plasminogen, is able to inhibit metastasis and neovascularization of tumors." (PMID 28188431, 2017). "uPA is a serine protease which converts the proenzyme plasminogen into the serine protease plasmin, thus making malignant cancer cells able to degrade BM and ECM." (PMID 29038785, 2017). "The uPA system is known to play a key role in cancer invasion and metastasis through the activation of plasminogen, which in turn induces ECM degradation." (PMID 27558531, 2016).